KPTN (kaptin, actin binding protein)
Description:
As part of the KICSTOR complex functions in the amino acid-sensing branch of the TORC1 signaling pathway. Recruits, in an amino acid-independent manner, the GATOR1 complex to the lysosomal membranes and allows its interaction with GATOR2 and the RAG GTPases. Functions upstream of the RAG GTPases and is required to negatively regulate mTORC1 signaling in absence of amino acids. In absence of the KICSTOR complex mTORC1 is constitutively localized to the lysosome and activated. The KICSTOR complex is also probably involved in the regulation of mTORC1 by glucose.
Synonyms: 2E4; KICS4; MRT41
Tractability: Antibody: the Human Protein Atlas places it where antibodies can reach. PROTAC: ubiquitination databases record sites on it; its protein half-life has been measured.
Gene: Protein-coding gene on chromosome 19 (47,475,141 to 47,484,265, reverse strand). Ensembl gene ENSG00000118162.
Subcellular location: Lysosome membrane; Cell projection, lamellipodium; Cell projection, stereocilium
Subcellular location (Human Protein Atlas): Plasma membrane; Nucleoplasm; Vesicles
Pathways (Reactome):
Cellular responses to stimuli: Amino acids regulate mTORC1
Gene Ontology:
Molecular function: actin filament binding; protein binding; actin binding
Biological process: cellular response to amino acid starvation; cellular response to glucose starvation; negative regulation of TORC1 signaling; protein localization to lysosome; actin filament organization
Cellular component: filamentous actin; KICSTOR complex; lamellipodium; postsynaptic actin cytoskeleton; lysosomal membrane; stereocilium; actin cytoskeleton
Genetic constraint (gnomAD): Loss-of-function variants: 36 observed, 48.11 expected, observed/expected ratio (o/e) 0.75, 90% interval 0.57 to 0.99. The upper end of that interval is the gene's LOEUF score, 0.99, which puts it in group 4 of 6, group 1 being the genes least tolerant of losing a copy. Missense variants: 518 observed, 553.17 expected, observed/expected ratio (o/e) 0.94, 90% interval 0.87 to 1.01. Synonymous variants: 270 observed, 240.53 expected, observed/expected ratio (o/e) 1.12, 90% interval 1.02 to 1.24.
Gene-disease validity (ClinGen):
ClinGen rates the evidence that KPTN causes each of these diseases.
complex neurodevelopmental disorder (autosomal recessive): Definitive. A disorder that involves more than one phenotype associated with the central nervous system, including but not limited to intellectual disability, autism, and seizures (epilepsy).
Homologues: Orthologues: chimpanzee KPTN (99% identical), macaque KPTN (94% identical), dog KPTN (93% identical), pig KPTN (90% identical), rabbit KPTN (89% identical), guinea pig KPTN (88% identical), rat Kptn (88% identical), mouse Kptn (88% identical), zebrafish kptn (58% identical).
Diseases named in the same sentence as KPTN in open-access papers:
KPTN is named in the same sentence as 19 diseases in open-access papers, as found by Europe PMC text mining. Sharing a sentence is not in itself a finding about the gene and the disease. The quoted sentences say what the papers report.
Macrocephaly (4 papers, 2014 to 2023). Occipitofrontal (head) circumference greater than 97th centile compared to appropriate, age matched, sex-matched normal standards. "Mutations in KPTN mutation are closely related to a syndrome characterized by macrocephaly, neurodevelopmental delay, and seizures." (PMID 36262473, 2022). "These KPTN mutations result in a distinctive clinical syndrome, and the presence of macrocephaly combined with global developmental delay should prompt the diagnostic analysis of KPTN in affected individuals from Anabaptist communities." (PMID 24239382, 2014). "Using linkage analysis and whole-exome sequencing on samples from families from the Amish community of Ohio, we have demonstrated that mutations in KPTN, encoding kaptin, cause a syndrome typified by macrocephaly, neurodevelopmental delay, and seizures." (PMID 24239382, 2014).
cognitive deficits (2 papers, 2023 to 2025). "Kptn knockout (KO) mice show increased mTOR signalling in the brain downstream of Kptn that is rapamycin sensitive and display many of the key KPTN-related disorder phenotypes, including brain overgrowth, behavioural abnormalities, and cognitive deficits." (PMID 40426219, 2025). "Kptn−/− mice display many of the key KPTN-related disorder phenotypes, including brain overgrowth, behavioural abnormalities, and cognitive deficits." (PMID 37437211, 2023).
atherosclerosis (1 paper, 2022). A disease characterized by the build-up of fatty material and calcium deposition in the arterial wall resulting in partial or complete occlusion of the arterial lumen. "For example, KPTN and RGS19, both novel genes displaying significant TWAS results for CAD—based on their genetically-modulated expression profiles of liver tissue—also showed significant association with various lipid traits as well as aortic lesion area in the atherosclerosis mouse model." (PMID 35175464, 2022).
hearing loss (1 paper, 2014). "A previous study of this molecule suggested a role at stereocilia tips, and so KPTN was proposed as a candidate gene for hearing loss." (PMID 24239382, 2014).
hepatocellular carcinoma (1 paper, 2025). A malignant tumor that arises from hepatocytes. "Notably, FBXO2 protein levels were substantially upregulated in patients with liver cancer, and FBXO2-mediated KPTN ubiquitination facilitated the progression of hepatocellular carcinoma (HCC)." (PMID 41401028, 2025).
myoclonic seizures (1 paper, 2025). "Of particular interest in this case is that several members of the maternal family were observed to have myoclonic seizures, raising the intriguing possibility that this newly identified KPTN mutation may lead to mild symptoms even in heterozygous carriers of this mutation." (PMID 41357736, 2025). "Of particular interest in this family is the discovery that on the maternal side of the family, from where the novel KPTN mutation has arisen, several family members who do not have KPTN-related disorder do show some mild symptoms, namely myoclonic seizures." (PMID 41357736, 2025).
Sleep apnea (1 paper, 2025). An intermittent cessation of airflow at the mouth and nose during sleep is known as sleep apnea. "These cases expand current knowledge of KPTN-related disorder by documenting a novel intronic variant, highlighting the need for further research into potential manifestations in heterozygous carriers, and describing sleep apnea as an observed clinical feature." (PMID 41357736, 2025).
tumor (3 papers, 2023 to 2026). "A comparison of these with the 683 KPTN tumor–upregulated genes revealed 130 consistently upregulated genes, including ECM components (COL4A1, COL4A2, COL12A1, VCAN, etc.)and YAP targets (ANKRD1, AXL, CYR61, F3)." (PMID 41480763, 2026). "Collectively, these data suggest OTUD3’s function in reducing tumor cell proliferation requires the presence of KPTN protein, and the ability of KPTN to inhibit tumor cell proliferation relies on the presence of its ubiquitination site." (PMID 38288086, 2023). "We propose a novel mechanism involving KPTN-mediated regulation of the mTORC1 signaling pathway, offering fresh insights into the occurrence and progression of tumor diseases driven by related genes." (PMID 38288086, 2023). "In summary, our experiments shed light on OTUD3’s intrinsic role in inhibiting tumor initiation and development, proposing a novel mechanism involving KPTN in mTORC1 pathway regulation." (PMID 38288086, 2023). "Interestingly, bulk RNA-Seq data revealed WNT7B upregulation in both KPTN tumors and organoids, where it functions as an essential niche factor for maintaining human pancreatic organoid cultures and supporting tumor growth." (PMID 41480763, 2026).
cancer (1 paper, 2026). A tumor composed of atypical neoplastic, often pleomorphic cells that invade other tissues. "We identified 683 human genes significantly upregulated in KPTN tumors (fold change >2, adjusted P [Padj] < 0.05), which are involved in proliferation, glycolysis, hypoxia, focal adhesion, as well as collagen formation, suggesting a more active cancer progression." (PMID 41480763, 2026).
KPTN also shares sentences with these, for which no sentence is quoted: developmental delay (3 papers); epilepsy (2); Neurodevelopmental delay (2); Anxiety (1); developmental and epileptic encephalopathies (1); focal epilepsies (1); liver cancer (1); microcephaly (1); neurodevelopmental disorder (1); Seizure (1).